GCH1 (GTP cyclohydrolase 1)
Diseases named in the same sentence as GCH1 in open-access papers (continued):
Sharing a sentence is not in itself a finding about the gene and the disease.
Parkinsonism (48 papers, 2009 to 2026). Characteristic neurologic anomaly resulting from degeneration of dopamine-generating cells in the substantia nigra, a region of the midbrain, characterized clinically by shaking, rigidity, slowness of movement and difficulty with walking and gait. "Transcriptome analysis of 605 Sardinians showed that the Parkinson's disease-predisposing variant was significantly associated with an increase in a shorter and inactive form of GCH1, whose presence is predicted to reduce the GCH1 decamer stability." (PMID 41667488, 2026). "For example, genetic and methylomic variation in YJEFN3 has shown associations with schizophrenia and common and rare genetic variants in GCH1 are associated with Parkinson’s disease." (PMID 33684137, 2021). "Another study of GCH1 single‐nucleotide polymorphisms revealed possible increased risk of Parkinson's disease." (PMID 29484265, 2018). "In this study, we made a rapid genetic diagnosis for two GCH1-associated DRD patients with prominent parkinsonism in one family, and two rarer TH-associated DRD siblings with long delay over 10 years from another unrelated family by exome sequencing." (PMID 25181484, 2014). "A 33-year-old Chinese DRD patient with pure parkinsonism were described, who had a heterozygous mutation in GCH1 gene." (PMID 25181484, 2014). "GCH1 mutations have also been shown to segregate in pedigrees with multiple individuals affected by isolated parkinsonism." (PMID 24993959, 2014). "Our results show that rare GCH1 variants are associated with an increased risk for Parkinson’s disease." (PMID 24993959, 2014). "We provide evidence that rare GCH1 coding variants should be considered as a risk factor for Parkinson’s disease." (PMID 24993959, 2014). "A better understanding of the relationship between GCH1 deficiency and Parkinson’s disease will shed light on the role of dopamine metabolism on nigral neuron survival, with potential therapeutic implications for patients." (PMID 24993959, 2014). "Further insight into GCH1-associated pathogenetic mechanisms will shed light on the role of dopamine metabolism in nigral degeneration and Parkinson’s disease." (PMID 24993959, 2014). "The frequency of GCH1 variants was evaluated in whole-exome sequencing data of 1318 cases with Parkinson’s disease and 5935 control subjects." (PMID 24993959, 2014). "Gch1 variants have recently been associated with the risk and age of onset of Parkinson’s disease." (PMID 39156629, 2024). "Interestingly, another DMP was related to the GCH1 gene, which encodes a key enzyme in dopamine synthesis and whose variants have been reported to be a risk factor for Parkinson’s disease." (PMID 38791483, 2024). "Other studies confirmed that parkinsonism is indeed relatively common in GCH1 mutation carriers (27%) and that the frequency of parkinsonism is dependent on the age of onset of dystonia, being more frequent in carriers with disease onset after the age of 15 years." (PMID 34360863, 2021). "It has been suggested that late-onset DRD might present clinically with parkinsonism, or alternatively, pathogenic GCH1 mutations may predispose to both diseases and carriers will develop any or both depending on other genetic or environmental factors." (PMID 34421783, 2021). "Common and rare variants of guanosine triphosphate cyclohydrolase 1 (GCH1) gene may play important roles in Parkinson’s disease (PD)." (PMID 32746945, 2020). "A significant proportion of early-onset PD patients manifest with dystonia; moreover, co-occurrence of DRD and parkinsonism has been reported in families with mutations of guanosine triphosphate cyclohydrolase 1 (GCH1) gene, which is a well-established disease-causing gene for DRD." (PMID 32746945, 2020). "The aim of this study was to further explore the relationship between GCH1 mutations and parkinsonism and consider whether adult GCH1 mutation carriers are at increased risk of developing neurodegenerative Parkinson’s disease." (PMID 24993959, 2014).
Parkinsonism (continued). "The question as to how the same variants known to cause a Mendelian disease may also exist as risk alleles in Parkinson’s disease may be explained by the well-known reduced penetrance of GCH1 pathogenic variants." (PMID 24993959, 2014). "An as-yet unpublished meta-analysis of existing genome-wide association study data has, however, identified GCH1 as a common low-risk locus (Singleton, personal communication), consistent with the hypothesis of a causal role for GCH1 in Parkinson’s disease." (PMID 24993959, 2014). "The second signal, represented by rs12323905-T (P-value = 8.17×10-08, beta = 0.30), colocalised with GCH1 splicing and Parkinson's disease signals." (PMID 41667488, 2026). "In conclusion, our study identified a rare non-coding variant in the GCH1 gene in a Chinese family with DRD and/or parkinsonism." (PMID 39801809, 2025). "Variants in GCH1 can reduce BH4 levels, impaire dopamine synthesis, and disrupt dopaminergic nigrostriatal neurotransmission, leading to, parkinson’s disease, and other related disorders." (PMID 39801809, 2025). "Variants in the GCH1 gene, encoding guanosine triphosphate cyclohydrolase, are associated with dopa-responsive dystonia (DRD) and are considered risk factors for parkinson’s disease." (PMID 39801809, 2025). "Our findings also demonstrated the downregulation of GTP cyclohydrolase 1 (GCH1), a known Parkinson’s disease (PD) risk gene." (PMID 36984847, 2023). "Other genes excluded from the PARK category, such as GBA1, GTP cyclohydrolase 1 (GCH1), and MAPT, were also significantly linked to PD or parkinsonism through meta-analyses of GWAS." (PMID 35720097, 2022). "For example, parkinsonism is generally detected with mutations in DYT genes (such as DYT/PARK-TAF1, DYT5/PARK- GCH1, DYT/PARK-ATP1A3, and DYT/PARK-PRKRA)." (PMID 35273550, 2021). "Our functional data provide complementary evidence for a role of GCH1 in Parkinson’s disease and other disorders characterized by abnormal aggregation and deposition of α-synuclein." (PMID 33311497, 2020). "One pedigree, presented with prominent parkinsonism, was misdiagnosed as Parkinson's disease until a known mutation in GCH1 (GTP cyclohydrolase 1) gene (NM_000161.2: c.631_632delAT, p.Met211ValfsX38) was found." (PMID 25181484, 2014). "For the “mutation-free” individuals, it is necessary to screen either deletions in the GCH1 gene, more genes in the dopamine pathway, Parkinson-related genes, or possibly even the whole genome, to identify the complete genetic background of DRD." (PMID 23762320, 2013). "Our data motivate experimental work to test whether modulating GCH1 expression or isoform ratio alters dopaminergic function in Parkinson's disease models." (PMID 41667488, 2026). "Rare heterozygous GCH1 variants have been associated with nigrostriatal cell loss, and DRD patients may exhibit additional movement disorders, including parkinsonism and spasticity." (PMID 39801809, 2025). "While GCH1 has been associated with neurological disorders such as Parkinson’s disease, it has never been linked with alphavirus disease pathogenesis." (PMID 36680176, 2022). "From the genetics perspective, parkinsonism is commonly seen in carriers of mutations in DYT genes, such as TAF1 (DYT3), ATP1A3 (DYT12) and PRKRA (DYT16), but especially in those involved in the dopamine synthesis pathway, GCH1 (DYT5a) and TH (DYT5b)." (PMID 34360863, 2021). "In fact, variants in GCH1 appeared significantly more frequently in idiopathic Parkinson’s disease patients than in controls, strongly suggesting the participation of BH4 metabolism in Parkinson’s disease physiopathology." (PMID 34423297, 2021). "The reported phenotypic overlap between PD patients with PARKIN mutation and rare forms of dystonia-parkinsonism, such as levodopa-responsive dystonia (DRD), prompts screening for PARKIN mutations along with GTP cyclohydrolase 1 and tyrosine hydroxylase in clinically diagnosed DRD patients." (PMID 30971883, 2019).
Parkinsonism (continued). "(2014) they found GCH1 gene could possibly have a correlation with Parkinson's disease via whole exome sequencing;." (PMID 29484265, 2018). "However, GCH1 proteins are decreased due to increased degradation of GCH1 by 26S proteasome or/and decreased biosynthesis during cardiovascular disease and in diabetes, Parkinson’s disease, or aging." (PMID 28596578, 2017). "Previous studies investigating the contribution of rare coding GCH1 variants in small cohorts of cases with Parkinson’s disease have reported negative results although these were insufficiently powered to draw conclusions." (PMID 24993959, 2014). "First, dopamine transporter imaging was not available for the cases with Parkinson’s disease with GCH1 variants identified in the exome sequencing study." (PMID 24993959, 2014). "Another study suggested GCH1 variants may lead to parkinsonism by unmasking subclinical nigral pathology, not by causing nigral neurodegeneration." (PMID 40672488, 2025). "Whether GCH1 mutation could be pathogenic to Parkinson's disease remained uncertain, but these results could possibly give us a new idea that parkinsonism may not necessary just be symptoms of DRD." (PMID 29484265, 2018). "Although Parkinson's disease is not regarded as a disorder of dopamine metabolism, the identification that GCH1 mutations can lead to Parkinson's disease as well as dopa-responsive dystonia suggests that biochemical depletion of dopamine is likely to have more complicated effects than once thought." (PMID 27017469, 2016). "We subsequently explored the possibility that pathogenic GCH1 variants could contribute to the risk of developing Parkinson’s disease, even in the absence of a family history for DOPA-responsive dystonia." (PMID 24993959, 2014). "The GCH1/BH4 metabolic pathway participates in the generation of reactive oxygen species and is important in many abnormal disease statuses including diabetes, hypertension, and Parkinson's disease." (PMID 36793373, 2023). "Additionly, there were a few reports about adult-onset DRD patients presented with pure parkinsonism in autosomal dominant DRD pedigrees though the genetic testing of GCH1 gene was not available at that time." (PMID 25181484, 2014). "We recommend that genetic counselling and testing for GCH1 should not be neglected in patients with pure parkinsonism." (PMID 25181484, 2014). "We hypothesize that the –22C > T substitution in the 5’ UTR of the GCH1 gene likely reduces GTP cyclohydrolase 1 levels, thereby limiting BH4 biosynthesis and impairing dopamine synthesis, which could contribute to the pathogenesis of DRD and/or parkinsonism." (PMID 39801809, 2025).
dopa-responsive dystonia (36 papers, 2006 to 2026). "Another example is GCH1-associated dopa-responsive dystonia (DRD, DYT/PARK-GCH1), in which reduced penetrance can also be observed, both in females and in males." (PMID 38835915, 2022). "Dopa-responsive dystonia (DYT/PARK-GCH1) develops due to pathogenic variants in the GCH1 gene, which codes for one of the enzymes in the dopamine synthesis pathway (GTP-cyclohydrolase 1)." (PMID 33876307, 2021). "Loss of function mutations in GCH1 cause the rare disorder dopa-responsive dystonia, which is managed clinically with oral dopamine replacement therapy." (PMID 33311497, 2020). "All BH4Ds are autosomal recessive disorders apart from AD-GTPCHD where heterozygous mutations in the GCH1 gene cause childhood-onset dopa-responsive dystonia with diurnal fluctuation." (PMID 32456656, 2020). "Although the GCH1 gene is mainly related to dopa-responsive dystonia, some missense variants in GCH1 have been also related to familial PD cases with an early onset of between 40 and 45 years." (PMID 32630630, 2020). "Targeted testing for GCH1, phenylalanine loading test, and repeat CSF neurotransmitter study ruled‐out GTP cyclohydrolase 1‐deficient dopa‐responsive dystonia (Segawa's disease)." (PMID 29120065, 2018). "A similar scenario has been documented in the GTP cyclohydrolase 1 gene (GCH1) in which heterozygous mutations are associated with Dopa-responsive dystonia (DRD)." (PMID 30425729, 2018). "To date, three genes have been convincingly shown to cause DOPA-responsive dystonia: GCH1 (GTP cyclohydrolase 1), TH (tyrosine hydroxylase) and SPR (sepiapterin reductase)." (PMID 23775978, 2013). "Hereditary diseases, such as DOPA-responsive dystonia and atypical phenylkenonuria, are attributed to GCH1 mutations." (PMID 19922668, 2009). "In addition, we found 3 patients with homozygous GCH1 variants who displayed the classic phenotype of dopa-responsive dystonia." (PMID 40134721, 2025). "Likewise, mutations in GCH1 typically manifest as dopa-responsive dystonia (OMIM #128230), but several cases manifesting with autosomal dominant PD have been reported." (PMID 39420034, 2024). "Mutations in the GCH1 gene are associated with childhood onset, dopa-responsive dystonia (DRD)." (PMID 24124602, 2013). "One of the most common genetic dystonia, dopa-responsive dystonia (DRD, DYT5), is mainly caused by the mutation of GCH1, which encodes GTP cyclohydrolase 1 (GCH1)." (PMID 32471089, 2020). "Mutations in GCH1 are the most common cause of DOPA-responsive dystonia (DYT5; OMIM#128230), a rare movement disorder that presents typically in childhood with lower limb dystonia and subsequent generalization." (PMID 24993959, 2014). "Loss-of-function mutations such as p.K224R have been shown to cause Dopa-responsive dystonia (DRD); however, variants in this gene have also been implicated in PD, perhaps through regulation of GCH1 expression." (PMID 34421783, 2021). "The autosomal dominant inheritance results in the typical phenotype of DRD, known as DYT5 or Segawa disease, which is caused by heterozygous mutations of guanosine triphosphate (GTP) cyclohydrolase I gene (GCH1)." (PMID 32117556, 2019). "A reduction in the TH protein level in the striatum has also been reported in autopsy studies of patients with Dopa-responsive dystonia (DRD), which is caused by an autosomal-dominant defect in the GCH1 gene encoding the rate-limiting enzyme for BH4 synthesis." (PMID 27798097, 2016). "Some examples are variants in the glucocerebrosidase (GBA), the sphingomyelin phosphodiesterase 1 (SMPD1), and the GTP cyclohydrolase 1 (GCH1) genes, responsible for Gaucher's disease, Niemann-Pick A disease, and dopa-responsive dystonia (DRD), respectively." (PMID 26942037, 2016).
dopa-responsive dystonia (continued). "GCH-1 serves as a remarkable illustration demonstrating how variations in a single gene can lead to distinct phenotypes like classic dopa responsive dystonia (DRD) and atypical DRD, contingent upon the degree of mutation severity and enzyme dysfunction rather than the quantity of mutations." (PMID 40134721, 2025). "Among the GCH1 variants identified by exome sequencing, two (Q110X and K224R) have been shown to cause GCH1 deficiency and DOPA-responsive dystonia in dominant pedigrees and two (V204I and M230I) have been reported in heterozygous sporadic or in recessive cases with DOPA-responsive dystonia." (PMID 24993959, 2014).
endothelial dysfunction (23 papers, 2011 to 2025). In vascular diseases, endothelial dysfunction is a systemic pathological state of the endothelium (the inner lining of blood vessels) and can be broadly defined as an imbalance between vasodilating and vasoconstricting substances produced by (or acting on) the endothelium. "Genetic variation of the GCH1 gene is associated with endothelial dysfunction and oxidative stress in T2DM patients." (PMID 25369080, 2014). "In the present study we have found that polymorphisms in the GCH1 gene, that can affect tetrahydrobiopterin synthesis, are associated with markers of endothelial dysfunction and oxidative stress." (PMID 25369080, 2014). "In our previous studies, we found that targeting the downregulation of GTP-cyclohydrolase 1 caused by IR to prevent endothelial dysfunction could be a new strategy for the prevention of RE." (PMID 33967762, 2021). "The animal model results showed that LIG could target Gch1 and play a protective role by improving endothelial dysfunction caused by IR." (PMID 33967762, 2021). "Our findings demonstrate that chloroquine treatment reverses endothelial dysfunction by preventing GCH1 degradation via suppression of CHIP-mediated ubiquitination, leading to improved NO synthesis despite unchanged eNOS protein levels." (PMID 39941119, 2025). "For instance, GCH1 inhibition reduces microglial inflammation, and it participates in endothelial dysfunction in atherosclerosis." (PMID 38993132, 2024). "The role of L-phenylalanine in binding pockets on GCH1-GFRP complexes in the treatment of endothelial dysfunction was also validated in a separate study." (PMID 39829954, 2024). "As the rate-limiting enzyme of de novo BH4 synthesis, the critical role of GTP cyclohydrolase 1 (GCH1) in maintaining eNOS function and preventing endothelial dysfunction has been established by us." (PMID 36399957, 2022). "Previous studies revealed that miR-133a in the vascular endothelium regulates endothelial dysfunction by targeting GCH1." (PMID 34402860, 2021). "Studies have demonstrated that the inhibition of aberrant miR-133a by lovastatin prevents endothelial dysfunction by targeting GTP cyclohydrolase 1, a critical enzyme for eNOS uncoupling in endothelial dysfunction." (PMID 31487802, 2019). "Here, the authors demonstrate that l-phenylalanine administration restores vascular function in a rodent model of hypertension, suggesting the GCH1-GFRP complex represents a rational therapeutic target for diseases underpinned by endothelial dysfunction." (PMID 29963647, 2018). "More recently, it has demonstrated that statins may inhibit aberrant miR-133a expression in the vascular endothelium to prevent endothelial dysfunction and consequent cardiovascular diseases by targeting GTP cyclohydrolase 1 (GCH1)." (PMID 28067828, 2017). "GCH1, a pivotal enzyme catalyzing BH4 production, plays a crucial role in atherosclerotic endothelial dysfunction." (PMID 38993132, 2024). "Currently, no reports have been found regarding the improvement in endothelial dysfunction or the prevention and treatment of RE by targeting Gch1." (PMID 33967762, 2021). "However, small molecules that mimic the allosteric effects of L-phe at the GCH1-GFRP interface but do not bind to phenylalanine hydroxylase could be developed, underpinned by endothelial dysfunction." (PMID 29963647, 2018).